EZH2 (enhancer of zeste 2 polycomb repressive complex 2 subunit)
Diseases named in the same sentence as EZH2 in open-access papers (continued):
Sharing a sentence is not in itself a finding about the gene and the disease.
cancer (continued). "Based on our data and the literature, we envision that EZH2 inhibitors may improve the efficacy of PARP1 inhibitors for new therapeutic approaches, as well as for current cancer treatment, leading to a more precise use of these classes of compounds." (PMID 29535829, 2018). "Finally, EZH2 has been shown to have a role in transcriptional repression through H3K27 tri-methylation and is considered a key potential target in many cancers." (PMID 29487714, 2018). "The enhanced expression of EZH2 in BTICs determines the downregulation of DNA damage repair proteins and the accumulation of genomic abnormalities that mediate deregulated signaling (RAF1-ERK-β-catenin) resulting in BTIC expansion and cancer progression." (PMID 30510924, 2018). "Interestingly, the collaboration of EZH2 and E2F1 in transcriptional regulation has been observed in various cancers." (PMID 28427185, 2017). "We identified consistently upregulated genes (such as E2F1, EZH2, FOXM1, MYBL2, PLK1, TTK, AURKA/B and BUB1) and consistently downregulated genes (such as SCARA5, MYOM1, NKAPL, PEG3, USP2, SLC5A7 and HMGCLL1) across various cancers." (PMID 28427185, 2017). "EZH2 interacts with both histone and non-histone proteins to modulate diverse physiological functions including cancer progression and malignancy." (PMID 28561778, 2017). "EZH2 is critical for maintaining CSC phenotypes in RCC, as well as in other cancer types." (PMID 28978010, 2017). "Here we reveal that EZH2, the functional enzymatic component of PRC2, which is responsible for addition of methyl groups to histone H3 at lysine 27 (H3K27), displays a particularly high recruitment towards METTL7A gene body in cancer cells." (PMID 28416772, 2017). "EZH2, a subunit of the polycomb repressive complex 2 (PRC2) catalyzing trimethylation of histone H3 lysine 27 (H3K27), induces epithelial-mesenchymal transition (EMT) in cancers." (PMID 28754964, 2017). "The polycomb group protein enhancer of zeste homolog 2 (EZH2) is a methyltransferase and the core catalytic element of polycomb repressive complex 2 (PRC2), which plays a critical role in the regulation of cancer initiation, progression, invasion, metastasis, and drug resistance." (PMID 28147317, 2017). "Our results suggest that inhibition of EZH2 may increase NKT cell numbers, and then could help to treat cancer." (PMID 28529687, 2017). "Aberrant activity of PRC2 can result from aberrant EZH2 expression, without chromosomal amplification, as a consequence of diverse aberrations which are present in cancer cells." (PMID 27239242, 2016). "It is intriguing to speculate that EZH2, as a chromatin modulator and part of PRC2, is involved in cancer stem cell maintenance through alteration of transcriptional programs." (PMID 27793053, 2016). "Based on the oncogenic role of NOTCH1 in cancer development and progression, we hypothesized that NOTCH1 is likely regulated by EZH2." (PMID 27049834, 2016). "Among 848 EZH2-bound lncRNAs in MKN45, the metastatic cell line among the three cell lines examined, we found HOTAIR and MALAT1, which are well documented for their involvement in cancer metastasis." (PMID 26871474, 2016). "Furthermore, other members of the SWI/SNF complex are frequently lost or mutated in cancers, and it will be of interest to investigate whether altered SWI/SNF activity through mutation or expression changes of a given complex subunit in general predicts sensitivity to EZH2 inhibition." (PMID 27391784, 2016). "Their results suggested that combined expression of embryonic stem cell markers EZH2 and SOX2 might be used to identify potential cancer stem cells as a minor (<10%) subgroup in CD44+ prostatic adenocarcinoma cells." (PMID 27447616, 2016). "EZH2 was shown to be important in SWI/SNF mutant cancers requiring both catalytic and non-catalytic functions." (PMID 27764181, 2016).
cancer (continued). "Enhancer of zeste homolog 2 (EZH2) is an essential component of the polycomb repressive complex 2 (PRC2), which is required for epigenetic silencing of target genes, including those affecting cancer progression." (PMID 26848980, 2016). "Immunohistochemistry analysis showed that β-catenin expression was distributed in the membrane of cancer cells and significantly decreased in MALAT1-shRNA group compared with control group, and Ezh2 expression demonstrated the lower expression level in cell nucleus after MALAT1 knockdown." (PMID 27015363, 2016). "Furthermore, a marked decrease in HMT activity and a decrease in EZH2 protein expression and trimethylation of H3K27 were noted in histones isolated from cancer cells treated with plant flavones." (PMID 27658199, 2016). "Using potent and selective EZH2 inhibitors, studies have recently shown that proliferation of several types of cancer cells was not significantly affected by pharmacological inhibition of EZH2/H3K27 methylation." (PMID 27316347, 2016). "We found that the Ezh2 expression level was notably elevated in cancer tissues compared with that in matched adjacent non-cancerous tissues (P=0.0024)." (PMID 27015363, 2016). "The subgroup analysis according to sample size did not change the significant association between high EZH2 expression and DFS of cancer patients." (PMID 25974088, 2015). "One of these compounds, wedelolactone, binds to EED with a high affinity (KD = 2.82 μM), blocks the EZH2-EED interaction in vitro, induces the degradation of PRC2 core components and modulates the expression of detected PRC2 downstream targets and cancer-related genes." (PMID 25944687, 2015). "Therefore, it would be interesting to find the role of EZH2-mediated epigenetic regulation in transcription of Pol III transcribed genes in physiological or pathological conditions, especially in cancers." (PMID 26038315, 2015). "EZH2 negatively regulates E-cadherin expression via trimethylation of H3K27 and transcriptional factor snail is required for EZH2-mediated E-cadherin repression in nasopharygeal cancer cells (NPC)." (PMID 26336990, 2015). "Mounting evidence demonstrated that EZH2 function as an oncogene and a negative prognosis factor involving in carcinogenesis in many human cancer types." (PMID 26378043, 2015). "Together with our findings, these data suggest that EZH2-regulated miR-200 and miR-30 family members may modulate cell survival and EMT in numerous different cancers." (PMID 25890085, 2015). "Second, cancer staging and EZH2 cut-off values were not consistent across studies, and the definitions of outcome measures were not provided in all reports." (PMID 25974088, 2015). "The majority (n = 52) of the malignant tumors stained positively, while all the investigated benign tumors were negative for EZH2." (PMID 26377323, 2015). "We examined whether EZH2 catalyzed H3K27 trimethylation (H3K27me3) is augmented in Karpas-422 and SUDHL4 lines compared to other cancer cell lines." (PMID 25605023, 2015). "The disruption of EZH2 and DNMT1 influenced tumorgenesis and cancer progression." (PMID 26362062, 2015). "EZH2 is the catalytic subunit of PRC2, which catalyzes histone H3 trimethylation on lysine 27 (H3K27me3), thereby promoting selective gene silencing in normal stem cells and cancer cells." (PMID 26553291, 2015). "First, this study analyzed the prognostic significance of EZH2 in various types of carcinoma, rather than a single specific type." (PMID 25974088, 2015). "Moreover, we also examined the effects of JARID2 knockdown in the status of histone H3 methylation and EZH2 recruitment on the regulatory regions of CDH1 and miR-200 family genes in another cancer cell line, HT29." (PMID 25542019, 2014). "Therefore these results together suggested that JARID2 was required for TGF-ß-dependent changes of histone H3 methylation and EZH2 recruitment on the specific target genes during TGF-ß-induced EMT process of A549 and HT29 cancer cell lines." (PMID 25542019, 2014).
cancer (continued). "Moreover, knocking down EZH2 expression suppresses the cell invasion by downregulating E2F1 and MMP9 in endometrial and in colorectal cancer." (PMID 25295088, 2014). "Enhancer of zeste homolog 2 (EZH2), a critical component of the polycomb repressive complex 2, has been found to be involved in multiple biological processes and is overexpressed in several types of cancer." (PMID 25295088, 2014). "EZH2, catalytic subunit of PRC2, is predominantly considered to trimethylates Lys 27 of histone H3, leading to silencing of target genes involved in cell cycle regulation, senescence, cell fate determination, cell differentiation and cancer." (PMID 25520914, 2014). "Currently, no EZH2 inhibitors are approved for treatment of human cancers; much effort has been made to develop EZH2 HMTase inhibitors." (PMID 25520914, 2014). "In addition to VASH1, the cellular networks enriched by EZH2 target genes in EOC cells include cell death, growth and proliferation and reproductive system development, and cancer." (PMID 23494175, 2013). "ERK/Akt also regulated EZH2 and E-cadherin to influence the EMT of cancer." (PMID 24168056, 2013). "EZH2 is not a canonical stem/progenitor marker in the prostate but has been involved in cancer stem cell maintenance in various diseases." (PMID 23675307, 2013). "EZH2, a core member of the Polycomb Repressor Complex 2 (PRC2), mediates transcriptional silencing by catalyzing the trimethylation of histone 3 lysine 27 (H3K27), which plays key roles in cancer initiation and progression." (PMID 24345883, 2013). "Enhancer of zeste homolog 2 (EZH2), the catalytic subunit of Polycomb Repressive Complex 2 (PRC2), is one of the most commonly up-regulated epigenetic regulators in different human cancers." (PMID 23826380, 2013). "EZH2 has recently been established as a driver oncogene, where it is involved in the aberrant hypermethylation of tumour suppressor genes (TSG) in multiple cancer types." (PMID 23967231, 2013). "Enhancer of zeste homolog 2 (EZH2), the histone methyltransferase of the Polycomb Repressive complex 2 catalyzing histone H3 lysine 27 tri-methylation (H3K27me3), is frequently up-regulated in human cancers." (PMID 23826380, 2013). "In particular, EZH2 is not expressed in the cholangiocytes or hepatocytes of livers without tumors, but is overexpressed in poorly differentiated carcinoma." (PMID 24179546, 2013). "Enhancer of zeste homolog 2 (EZH2) is a mammalian histone methyltransferase that contributes to the epigenetic silencing of target genes through methylation and promotes proliferation and metastasis of cancer cells." (PMID 22662197, 2012). "An increased expression of EZH2 has been shown to correlate with proliferation of cancer cells, but its relevance in PAH is not known." (PMID 22662197, 2012). "EZH2 (polycomb group protein enhancer of zeste homolog 2) is the catalytic subunit of the polycomb repressive complex 2 (PRC2) and is overexpressed in a variety of human cancers." (PMID 22272343, 2012). "Therefore, the transcriptional repression of TIMP2 and TIMP3 by EZH2 likely enhances ECM degradation and angiogenesis but reduces apoptotic activity, favoring cancer cell invasion and metastasis." (PMID 22272343, 2012). "TIMP3 mRNA levels were found to be ∼10–13-fold higher in the cancer cells treated with EZH2-specific shRNA (sh1) than control cells untreated with the shRNA, and as a result, TIMP3 protein levels were significantly increased by knockdown of EZH2 expression." (PMID 22272343, 2012). "Mechanistically, the silencing of all these H3K27me3 gene groups may involve EZH2, which is frequently over-expressed in CRC and other cancer types and is able to interact with and recruit DNA methyltransferases." (PMID 22011431, 2011).
cancer (continued). "This may suggest that the pharmacological approach we have demonstrated for inhibiting EZH2 and reactivating CDKN1C might have broad application for cancer therapy." (PMID 19340297, 2009). "Combining PARP inhibition with blockade of O-GlcNAcylation or EZH2 might offer a strategy to radiosensitize proliferating HR-proficient cancers while sparing non-cycling normal tissues." (PMID 41778489, 2026). "Additionally, unlike other cancers, EZH2 expression in MM is mostly regulated by epigenetic mechanisms rather than gain-of-function mutations." (PMID 40890111, 2025). "Moreover, principal component analysis of single-cell RNA-sequencing data of 65,655 GSCs and 14,207 GBM cells revealed that the area where CYP3A5 was highly expressed harbored cells that also markedly expressed cancer stem cell markers, such as PROM1, SOX2, EZH2 and NOTCH1." (PMID 39754188, 2025). "The chromatin modifier enhancer of zeste homolog 2 (EZH2) protein, a subunit of the polycomb repressor complex 2 (PRC2), catalyzes histone H3 lysine 27 trimethylation (H3K27me3) of target gene promotors and silences the transcription of several cancer-related genes via chromatin reorganization." (PMID 39941804, 2025). "Several studies have identified non-canonical roles for EZH2 in a variety of cancer types." (PMID 40791365, 2025). "Indeed, treatment with the proteasomal inhibitor MG132, but not the lysosomal inhibitor chloroquine, fully rescued EZH2 protein expression in cancer cells either with Usp22 deletion or treated with the USP22 small-molecule inhibitor S02." (PMID 41252204, 2025). "We did not detect EZH2, which confers polycomb silencing in cancer cells, on the promoters." (PMID 40717771, 2025). "Therefore, in murine cancer models, anti-CTLA4 and EZH2 inhibition could cooperate to provide strong anti-cancer immune responses." (PMID 39227959, 2024). "Additionally, compound 91 exhibited significant antiproliferative activities against SWI/SNF-mutant cancer cells that are dependent on the enzymatic and nonenzymatic activities of EZH2." (PMID 38389844, 2024). "The methylated K20 is recognized by specific methyl lysine reader L3MBTL3 to promote EZH2 for ubiquitin-dependent proteolysis by the CRL4DCAF5 ubiquitin E3 ligase complex, resulting in the disassembly of the PRC2 complex and reduction of H3K27 trimethylation in animals, MEFs, and cancer cells." (PMID 38346162, 2024). "In addition, several studies have demonstrated that CDK1, through phosphorylation of BUB1, EZH2 and PPP1CA, alters cell cycle regulation, chromosome segregation, epigenetic control, and DNA replication, leading to cell dysfunction and diseases such as cancer." (PMID 38831458, 2024). "Some downregulated genes (EHF and MMP14), mainly involved in proliferation and cancer development, were not restored upon EZH2 inhibitor treatment, and some that were upregulated in KO samples retained or even increased their high expression after treatment (EFCAB6 and CDKN2A)." (PMID 38672463, 2024). "EZH2 can also collaborate with DNA methyltransferases (DNMTs) to reinforce gene silencing through DNA methylation and Polycomb group targets are more likely to have cancer-specific promoter DNA hypermethylation compared to non-targets." (PMID 39769907, 2024). "This expands our findings in another cancer model, where the more pronounced downregulation of PTEN may result from a combination of genetic alterations and transcriptional repression mediated by the YAP/MYC/EZH2 repressive complex." (PMID 39455556, 2024). "As several cancers do not respond to EZH2 enzymatic inhibitors, triggering EZH2 degradation may represent a more efficacious method to inhibit EZH2." (PMID 39769907, 2024). "Therefore, exploring a combined drug strategy of inhibiting EZH2 and HIF-1α together could potentially improve the effectiveness of cancer treatment." (PMID 38911968, 2024). "In addition to EZH2, STAT3 has also been found to be hyperactive in numerous cancers." (PMID 39204206, 2024).
cancer (continued). "HIF‐1α and EZH2 interact to form a negative feedback loop that promotes cancer development." (PMID 38072662, 2024). "In addition to cancer, EZH2 plays a role in the pathogenesis of several non-oncologic diseases, including PAH." (PMID 37461108, 2023). "In addition, by integrating the chromatin profiles from ENCODE, the authors also found an enrichment of the PRC2 subunits EZH2 and SUZ12 in the promoters that are gained/lost in cancer, highlighting the role of PRC2 in maintaining the cancer chromatin landscape." (PMID 36653445, 2023). "Moreover, EZH2, along with the potential epigenetic regulator lysine-specific demethylase 2B (KDM2B), dampens colorectal cancer migration, invasion, and maintenance of cancer stem cells via the PI3K/AKT pathway." (PMID 36672374, 2023). "Considering the limited efficacy of epigenetic inhibitors in cancer patients, which primarily target enzymatic activity, a more focused investigation into EZH2’s non-canonical functions may identify more effective therapeutic strategies." (PMID 37664059, 2023). "While we were initially interested in HKMTI-1-005 as an EZH2 inhibitor, evidence of a role for G9A in AML pathogenesis and maintenance of a cancer stem cell phenotype suggested that the dual inhibitory activities of HKMTI-1-005 could be therapeutically advantageous in the context of AML." (PMID 37035245, 2023). "Considering these discoveries, targeting the degradation of EZH2, or its post-translational modifiers could be a promising therapeutic approach for cancers that rely on these non-canonical interactions." (PMID 37664059, 2023). "More importantly, there are no clinical trials targeting EZH2 PTMs for cancer treatment." (PMID 36672374, 2023). "Although both CHD4 and EZH2 play roles in epigenetics, it has not been determined whether the two modifiers cooperate during cancer progression." (PMID 36681835, 2023). "In addition to its well-documented action as a competitively endogenous RNA (ceRNA) sponging miRNAs in human cancers, SNHG15 was reported to act in the nucleus in concert with EZH2 (Enhancer of zeste homolog 2), which is known to catalyze repressive trimethylation at histone 3 (H3K27me3)." (PMID 37880732, 2023). "However, some cancers are independent of its catalytic activity and do not response after treatment or easily acquired drug resistance with EZH2 inhibitors." (PMID 36642705, 2023). "Furthermore, miR-150 regulates cancer cell migration by affecting multiple effectors including matrix metalloproteinases (MMP14 and MMP13), cell adhesion molecules (ITGA3, ITGA6), transcription factors (MYB), and epigenetics factors (HMGA2 and EZH2)." (PMID 37924077, 2023). "In conclusion, in HCT116 and HT29 cell strains, knocking out EZH2 may promote expressions of proteins related to the Wnt/β-catenin signaling pathway through inhibiting RUNX3, which in turn suppresses the cancer cellular proliferation, invasion and migration while promoting apoptosis." (PMID 38048186, 2023). "In summary, our present study reveals a novel function of PROX1 in cancer cell metabolism, i.e., PROX1 recruits EZH2 to the SIRT3 promoter and represses SIRT3 transcription, which may represent the molecular mechanism underlying the observed biological consequences." (PMID 36594098, 2023). "EZH2, EHMT2, and SMYD3 are vital epigenetic regulators that could be targeted for cancer therapy." (PMID 35300417, 2022). "SIRT1 may facilitate cancer progression by epigenetically modulating the polycomb repressor complex 4 (PRC4) comprising DNMT1, DNMT3b, polycomb group (PcG) proteins, embryonic ectoderm development isoform 2 (EED2), and enhancer of zeste homolog 2 (EZH2)." (PMID 35054489, 2022). "EZH2, one core member of the Polycomb Repressive Complex 2 (PRC2), acts as a critical regulator in epigenetic mediation of genes via catalyzing trimethylation of Lys-27 of histone H3 (H3K27me3), which serves as a crucial mediator in cancer development and aggressiveness." (PMID 35802620, 2022).